METTL3 (methyltransferase 3, N6-adenosine-methyltransferase complex catalytic subunit)
Diseases named in the same sentence as METTL3 in open-access papers (continued):
Sharing a sentence is not in itself a finding about the gene and the disease.
gastric cancer (continued). "Further, the same results could be seen in other cancer cell line (e.g. SGC-7901, a gastric cancer cell line), knocking down of METTL3 also resulted in the suppression of cell migration or invasion abilities, besides that, the suppression of cell proliferation could also be observed." (PMID 31492150, 2019). "In conclusion, our study reveals that down-regulation of METTL3 inhibits the proliferation and mobility of human gastric cancer cells and leads to inactivation of the AKT signaling pathway, suggesting that METTL3 may be a potential target for the treatment of human gastric cancer." (PMID 30886897, 2019). "In conclusion, our results suggest that down-regulation of METTL3 inhibits cell migration, migration and invasion in human gastric cancer in vitro, which may be mediated by modifying gene expression to promote apoptosis and inactivating the AKT signaling pathway." (PMID 30886897, 2019). "METTL3-mediated hyper-methylation promotes gastric cancer through the HDGF axis, positioning METTL3 as both prognostic biomarker and therapeutic target." (PMID 41501031, 2026). "Notably, highly expressed METTL3 promotes gastric cancer (GC) cell liver metastasis by stabilizing HDGF mRNA via m6A." (PMID 41446042, 2025). "Another subunit of complex I of the ETC, NDUFA4, can be regulated by METTL3 and IGF2BP1, resulting in increased glycolysis, oxidative metabolism and gastric cancer cell progression." (PMID 41373022, 2025). "High expression of METTL3, METTL14, FTO, YTDHF1-2 and IGF2BP1, in gastric cancer, facilitates tumor immune evasion by maintaining the stability and expression of PD-L1 transcripts." (PMID 41228380, 2025). "The m6A RNA modifications and their regulators—including METTL3, ALKBH5, FTO, YTHDFs, hnRNPA2B1, and IGF2BP2—have particularly emerged as key drivers of chemotherapy resistance in gastric cancer." (PMID 41228380, 2025). "In gastric cancer, the upregulation of WTAP, a subunit of the METTL3 complex, boosts TGF-β expression." (PMID 40675967, 2025). "Conversely, elevated expression of METTL3 was determined in AML, bladder cancer, gastric cancer, and liver cancer, where it had been suggested to function as an oncogene, suggesting critical mechanisms for tumor progression." (PMID 41157107, 2025). "In gastric cancer (GC) and in head and neck squamous cell carcinoma (HNSCC), METTL3 upregulates centromere protein F (CENPF), ensuring an adequate blood supply for rapidly dividing tumor cells." (PMID 39098905, 2024). "In gastric cancer, m6A reader HNRNPA2B1 directly bound m6A sites of METTL3-methylated CENPF mRNA and promoted the mRNA stability, ultimately GC angiogenesis and metastasis through activating the FAK/MAPK axis." (PMID 39691597, 2024). "In this review, we focus on the potential mechanism of METTL3 in gastric cancer, and through our analysis, we suggest that targeting METTL3 could be a new therapeutic tool for treating GC." (PMID 39678510, 2024). "LINC0047 was shown to recruit the m6A writer METTL3 and to increase m6A modification on PTEN, decreasing PTEN stability, and inducing gastric cancer." (PMID 39280246, 2024). "On the contrary, after knocking out expression of METTL3, the activity of the YAP1 signaling pathway and the proliferation and metastasis of gastric cancer were inhibited by modifying the m6A RNA modification level of the YAP1 gene." (PMID 39009956, 2024). "In GC induced by exposure to environmental chemical carcinogens, METTL3 promotes the expression of SNHG7 by increasing the m6A methylation level of the lncRNA SNHG7 and promotes the malignant progression of gastric cancer." (PMID 39678510, 2024). "When METTL3 is downregulated, the AKT signaling pathway cannot be activated properly, inhibiting the proliferation, migration, and invasion ability of gastric cancer cells." (PMID 38856795, 2024). "miR-1269b, through its regulatory control over methyltransferase-like 3 (METTL3), exerts inhibitory effects on gastric-cancer development." (PMID 38542354, 2024).
gastric cancer (continued). "For instance, certain researchers have detected that METTL3 methylation of basic leucine zipper ATF-like transcription factor (BATF) mRNA inhibits its expression in gastric cancer (GC), and low expression of BATF mRNA is significantly associated with postoperative recurrence of GC." (PMID 39054967, 2024). "For instance, in gastric cancer, HBXIP is highly expressed and enhances METTL3 expression, which in turn leads to MYC mRNA methylation and subsequent translation, thereby promoting proliferation and cell migration." (PMID 38444581, 2024). "High levels of METTL3 can predict poor overall survival (OS) and progression-free survival (PFS) in cancer patients, such as those with gastric cancer, ESOC, OSCC (p = 0.002), and other cancers." (PMID 36835633, 2023). "Mechanistically, METTL3‐mediated m6A modification on the proto‐oncogene c‐Myc transcript resulted in increased MYC expression and gastric cancer progression." (PMID 35560957, 2023). "Of note, LINC00470 recruits METTL3 to drive m6A methylation of PTEN mRNA, leading to YTHDF2-dependent PTEN mRNA decay and finally promoting metastasis in gastric cancer." (PMID 37369946, 2023). "In this axis, METTL3 and the methylation regulation of ncRNAs by CLU4B play an important role in the development of gastric cancer." (PMID 37781524, 2023). "Therefore, continued exploration of METTL3 or association of METTL3 with “specific sites” in ANGPTL3 mRNA might contribute to the development of new cancer therapies and lead to the development of a new pathway for effective METTL3 inhibition in gastric cancer." (PMID 37344779, 2023). "Previous studies indicated that in human gastric cancer cells, high expression of METTL3 stimulates the expression of GLUT4 and ENO2 via the METTL3/HDGF axis, thereby promoting tumor angiogenesis and glycolysis." (PMID 36347025, 2022). "METTL3 induced proliferation, migration, angiogenesis and tumorigenesis via inhibition of ADAMTS9 and modification of YAP1 and KLF2 in gastric cancer." (PMID 36003776, 2022). "For instance, METTL3 facilitated angiogenesis and carcinogenesis by m6A-mediated ADAMTS9 suppression in gastric cancer." (PMID 36476503, 2022). "An oncogenic role for METTL3 has been suggested in several cancers, with high levels of METTL3 expression reported in acute myeloid leukaemia (AML), gastric cancer and hepatocellular carcinoma (HCC)." (PMID 36733939, 2022). "For example, METTL3-mediated m6A modification destabilizes SOCS2 mRNA in HCC and BATF2 mRNA in gastric cancer and promotes the translation of epidermal growth factor receptor (EGFR) and the Hippo pathway effector TAZ in human lung cancer cells." (PMID 35456475, 2022). "For gastric cancer, P300-mediated H3K27 acetylation activation in the METTL3 promoter induces METTL3 transcription." (PMID 36424383, 2022). "Through our study, we found that TRA2A, METTL3, ALKBH5 and TYHDC2 were significantly down-regulated in gastric cancers cells." (PMID 36003776, 2022). "Knockout METTL3 significantly reduces the m6A levels of MCM5 and MCM6, thus inhibiting carcinogenic of gastric cancer." (PMID 35022030, 2022). "METTL3 enhances the stability of ZMYM1 as facilitated by HuR via m6A and activates the EMT to promote the metastasis of gastric cancer." (PMID 35945641, 2022). "For instance, lncRNA THAP7-AS1, which exerts oncogenic functions in gastric cancer, was transcriptionally activated by SP1 and then stabilized by METTL3-mediated m6A modification." (PMID 36309694, 2022). "For example, METTL3 stimulates the m6A modification of HDGF mRNA to increase its expression and then trigger the glycolysis in gastric cancer cells." (PMID 35832094, 2022). "To validate the relationship between METTL3 and PD-L1 in gastric cancer cells, we performed the western blotting to measure the expression levels of PD-L1 in HGC-27 and BGC-823 cells after METTL3 overexpression or depletion." (PMID 36003776, 2022).
gastric cancer (continued). "Interestingly, p300 was demonstrated to be a transcription factor that could directly activate METTL3 transcription in neonatal rat cardiomyocytes and human gastric cancer, which was consistent with our finding that the transcriptional coactivator p300 could enhance the expression of METTL3." (PMID 36536495, 2022). "METTL3 and METTL14 can regulate the progression of multiple types of cancer, including bladder cancer, gastric cancer, cervical cancer, hepatocellular carcinoma, and pancreatic cancer." (PMID 35012593, 2022). "Methyltransferase like 3 (METTL3) is a key catalyst in m6A modification and plays a carcinogenic role in a variety of cancers, such as stomach cancer, bladder cancer, and pancreatic cancer." (PMID 34537760, 2021). "The writer METTL3 and METTL14 were reported to promote tumorigenesis in hepatocellular carcinoma and acute myeloid leukemia (AML), but have the opposite effect in gastric cancer." (PMID 33796449, 2021). "Collectively, these findings indicate that METTL3 can play a tumor-promoting role in NSCLC, gastric cancer, hepatoblastoma, and breast cancer." (PMID 34108450, 2021). "Similarly, decreased m6A methylation due to decreased METTL3 and increased FTO was also associated with increased tumorignesis in gastric cancer (GC)." (PMID 33814008, 2021). "METTL3 promotes mRNA methylation, enhances the stability of HDGF and ZMYM1 and promotes gastric cancer metastasis." (PMID 34094960, 2021). "In addition, reducing m6A methylation could activate oncogenic Wnt/PI3K-Akt signaling and promote malignant phenotypes of gastric cancer cells; moreover, METTL3 knockdown could inhibit the level of total RNA methylation of m6A, cell proliferation, and migration of gastric cancer cells." (PMID 33490266, 2021). "There is evidence that the PI3K/AKT/mTOR pathway mediates the function of m6A “writers” METTL3 and METTL14 in the progression of gastric cancer and retinoblastoma." (PMID 34088349, 2021). "After the knocking out of METTL3, the activity of the YAP1 signaling pathway and the proliferation and metastasis of gastric cancer were inhibited by regulating the m6A modification level of the YAP1 gene." (PMID 34394353, 2021). "Subsequently, colony formation assay was used to detect the significantly higher number of gastric cancer cells containing METTL3 in AGS and MKN-45 cell lines than in the METTL3 gene silencing and the other two control groups." (PMID 34394353, 2021). "Notably, METTL3 also participates in EMT in gastric cancer (GC), ovarian cancer and prostatic cancer." (PMID 32733807, 2020). "In agreement with the oncogenic functions of METTL3 in HCC, similar observations have recently been reported in several other types of cancer, namely, AML, GMB, bladder cancer, gastric cancer, and breast cancer." (PMID 33072775, 2020). "However, roles of m6A and its regulator METTL3 on non-coding RNA in gastric cancer are unknown." (PMID 33037176, 2020). "These modifications can be written by METTL3 or METTL14 and can be erased by ALKBH5 and regulate the tumorigenesis of leukemia, pancreatic cancer, endometrial cancer and gastric cancer." (PMID 31722709, 2019). "However, the presence of Mettl3 diminishes the stability of ADAMTS9 mRNA through an m6A-YTHDF2-dependent pathway, consequently promoting angiogenesis and carcinogenesis in gastric cancer." (PMID 41517663, 2026). "Mettl3 significantly affects the malignant process of gastric cancer through modifications of both mRNA and non-mRNA." (PMID 41517663, 2026). "Since METTL3 is known to regulate TGF-β signaling in lung and gastric cancers, and SMAD4 is a critical mediator of TGF-β signaling, we checked the expression levels of a few downstream effectors of SMAD4-dependent TGF-β signaling in METTL3-depleted SCC-25 cells, by western blot analysis." (PMID 40338154, 2025).
gastric cancer (continued). "Studies have found that METTL3 upregulates the m6A level of heparin binding growth factor (HDGF) mRNA, and then enhances its stability and promotes its expression through IGF2BP3, thereby increasing tumor angiogenesis and promoting gastric cancer metastasis." (PMID 40356596, 2025). "While established mechanisms of OXA resistance in gastric cancer involve JUNB-mediated MAPK hyperactivation, EphA2-induced EMT, METTL3-dependent DNA repair/stemness maintenance, and LINC00641-regulated autophagy, our study reveals a distinct immunosuppressive axis mediated by OASL." (PMID 41271618, 2025). "The oncogene role of METTL3 in AML has been well-established and its overexpression and oncogenic activity have subsequently been revealed in a variety of cancer types, including hepatocellular carcinoma, gastric cancer, and non-small cell lung cancer." (PMID 40356909, 2025). "Consistently, other groups discovered other target genes of METTL3-m6A such as MYC target genes, ZMYM1 (stability is enhanced by HuR) and SEC62 (stability is enhanced by IGF2BP1) in the cell proliferation and EMT progression in gastric cancer." (PMID 40734692, 2025). "Finally, in what concerns WTAP, it stabilizes the METTL3/METTL14 complex, and its overexpression in gastric cancer predicts poor prognosis and therapy resistance." (PMID 41228380, 2025). "METTL3 is involved in the m6A modification of the nuclear protein DEK, which improves the stability and expression of DEK, thereby promoting the proliferation and migration of gastric cancer (GC) cells." (PMID 41256854, 2025). "METTL3, METTL4, and KIAA1429 are the most common methyltransferases for m6A, playing a key role in regulating the expression of related genes in the context of gastric cancer resistance." (PMID 41584846, 2025). "Previous studies have found that METTL3 may promote EMT in GC by regulating the m6A level of KLHL5, leading to the distant metastasis of gastric cancer, especially lung metastasis." (PMID 39195675, 2024). "By constructing and transfecting the plasmid expressing methyltransferase-like 3 (METTL3) fused with catalytically inactivated Cas13 (dCas13b) and guide RNA targeting specific methylation sites of lncRNAs, we obtained gastric cancer stem cells with site-specific methylation of lncRNAs." (PMID 38600465, 2024). "In gastrointestinal tumors, miR-4429 has been reported to reduce METTL3 expression in gastric cancer, and another study reported that HOXA10 increases Smad2/3 expression in the nucleus and promotes METTL3 deposition to regulate the progression of EMT in gastric cancer." (PMID 38166703, 2024). "In gastric cancer, the enhancement of ZMYM1 mRNA stability by METTL3 was similarly dependent on its m6A catalytic activity, and enrichment of ZMYM1 could initiate the EMT procedure." (PMID 38221933, 2024). "In addition, both METTL3 and IGF2BP2 are positively correlated with STAT5A in human gastric cancer tissue samples." (PMID 38879589, 2024). "METTL3 mediates the m6A modification of DEK mRNA, which binds to the DEK 3’UTR through m6A, resulting in an increase in the stability of DEK mRNA and promoting DEK expression, promoting gastric cancer cell growth and metastasis." (PMID 39289775, 2024). "Therefore, the relationship between METTL3 and MYC in gastric cancer is still unclear and still needs further exploration." (PMID 39678510, 2024). "Both METTL3 and WTAP accelerates the Warburg effect of gastric cancer." (PMID 36855123, 2023). "In contrast, METTL3 overexpression elevates m6A methylation in ZMYM1 mature mRNA, stabilizes ZMYM1 mature mRNA, and enhances its protein expression level, thus promoting invasive metastasis of gastric cancer." (PMID 38102645, 2023). "Furthermore, METTL3 enhances SPHK2 expression to increase KLF2 ubiquitination-mediated degradation and promote malignant gastric cancer progression." (PMID 37996892, 2023).
gastric cancer (continued). "Additionally, lncRNA ARHGAP5-AS1 can recruit METTL3 to stimulate ARHGAP5 mRNA m6A modification and stabilize ARHGAP5 mRNA, leading to chemoresistance in gastric cancer." (PMID 37437245, 2023). "miR-4429 targeted and repressed METTL3 to inhibit m6A-mediated stabilization of SEC62, a component belonging to tetrameric Sec62/Sec63-subcomplex of Sec-complex, thus hindering proliferation and encouraging apoptosis in gastric cancer cells." (PMID 36614216, 2023). "So far, the basic research about stomach cancer has not involved PP2Acα/PPP2CA except that PP2Acα plays an antineoplastic role through the ATM/METTL3 Axis in Cheng’s research." (PMID 36870954, 2023). "In gastric cancer (GC), previous researches on the expression and role of METTL3 and METTL14 were not consistent, and their specific function and mechanism have remained elusive." (PMID 36866236, 2023). "METTL3 enhances PARP1 RNA stability, which heightens the activity of the base excision repair pathway and effective repair of oxaliplatin-induced DNA damage in tumor cells, further promoting oxaliplatin resistance in CD133+ gastric cancer stem cells." (PMID 37996892, 2023). "In gastric cancer, YTHDF1 recognized m6A modified SPHK2 mRNA that was catalyzed by METTL3." (PMID 36291811, 2022). "Several studies have reported that progression of GC is promoted by m6A writers, for example, METTL3-mediated m6A modification of some mRNA (HDGF, SPHK2, and MYC), which ultimately promotes gastric cancer progression, thus, exhibiting a prognostic significance." (PMID 35778697, 2022). "Survival analysis of patients showed that METTL3 (a writer) is a prognostic factor for poor outcomes in HCC, thyroid carcinoma, pancreatic cancer, CRC, gastric cancer, and colorectal cancer." (PMID 35186927, 2022). "For example, METTL3 regulates SOX2 mRNA in glioma stem cell maintenance and colorectal tumor progression, LEF1 in osteosarcoma progression, AFF4/NF-kB/MYC in bladder cancer, and SPHK2 in gastric cancer." (PMID 36183833, 2022). "Then, cell proliferation tests were performed on human gastric cancer cell lines AGS and MKN-45, revealing that the cell proliferation of both cell lines increased gradually and the amplitude of this proliferation decreased with the silencing of METTL3." (PMID 34394353, 2021). "The detection of mRNA levels of m6A-modified enzymes (METTL3, WTAP, METTL14, VIRMA, RBM15, FTO, and ALKBH5) in gastric cancer tissues and adjacent tissues showed that the mRNA level of METTL3 was significantly higher in gastric cancer tissues." (PMID 34394353, 2021). "After lentiviral transfection, METTL3 silencing in AGS (human gastric adenocarcinoma cell line AGS) and MKN-45 (human gastric cancer cell line MKN-45) gastric cancer cell lines directly inhibited the proliferation, aggressiveness, and migration of gastric cancer cells." (PMID 34394353, 2021). "Therefore, we suspect that METTL3/miR-17-92 cluster activates mTOR pathways by targeting PTEN and TMEM127 in gastric cancer progression." (PMID 33037176, 2020). "In addition, the expression of METTL3, a “writer”similar to WTAP, is higher in gastric cancer due to p300-mediated H3K27 acetylation of the METTL3 promoter." (PMID 32998774, 2020). "In addition, a reduction in m6A modifications following METTL3 depletion represses the PI3K-AKT signaling pathway and attenuates the proliferation and migration of human gastric cancer cells." (PMID 32121289, 2020). "Here, we investigated the biological function of METTL3/m6A in regulating ncRNA and defined a novel pathway for m6A-dependent primary microRNA (miRNA) maturation and AKT/mTOR activation in gastric cancer, which could be counteracted by everolimus." (PMID 33037176, 2020). "So far, there has been no study reported the regulating function of METTL3 on ncRNA in gastric cancer." (PMID 33037176, 2020).